RPN1 (ribophorin I)
Diseases named in the same sentence as RPN1 in open-access papers (continued):
Sharing a sentence is not in itself a finding about the gene and the disease.
infection (3 papers, 2017 to 2021). The state of being infected such as from the introduction of a foreign agent such as serum, vaccine, antigenic substance or organism. "The pro-viral role of TER94 and Rpn1 was investigated further by performing dsRNA knockdowns (silencing did not affect cell viability), followed by infection at 24 hpt with ZIKV PE24376, a patient-derived ZIKV isolate." (PMID 33986255, 2021). "We then found that RNAi targeting each of four other OST complex components, ribo-1/ribophorin I, stt-3/STT3, ostb-1/OST48 and ostd-1/ribophorin II, substantially reduced worm survival under PA14 infection." (PMID 32130226, 2020).
RPN1 also shares sentences with these, for which no sentence is quoted: breast invasive ductal carcinoma (2 papers); lung carcinoma (2); Myelodysplasia (2); acute erythroid leukemia (1); acute megakaryoblastic leukemia (1); acute myeloid leukemia (1); Acute myelomonocytic leukemia (1); acute promyelocytic leukemia (1); adenocarcinoma (1); clear cell renal adenocarcinoma (1); colon adenocarcinoma (1); colon cancer (1); esophageal squamous cell carcinoma (1); hereditary non-polyposis colorectal cancer (1); invasive breast carcinoma (1); lung squamous cell carcinoma (1); lymphoid leukemia (1); Lynch syndrome (1); medullary breast carcinoma (1); myeloid neoplasm (1); myeloproliferative diseases (1); non-small cell lung carcinoma (1); oesophageal adenocarcinoma (1); oral cancer (1); ovarian serous adenocarcinoma (1); parathyroid adenoma (1); polycythaemia vera (1); prostate adenocarcinoma (1); prostate tumor (1); rectal cancer (1).
A further 2 diseases each share a sentence with RPN1 in 1 paper.